ALKBH5 (alkB homolog 5, RNA demethylase)
Diseases named in the same sentence as ALKBH5 in open-access papers (continued):
Sharing a sentence is not in itself a finding about the gene and the disease.
melanoma (continued). "During Anti–PD-1 treatment for melanoma and colorectal carcinoma, tumor cell expression of ALKBH5 regulates extracellular lactate content and then affects Tregs and MDSCs accumulation in the TME." (PMID 35063010, 2022). "Then, we analyzed the somatic mutations of 21 m6A regulators in TCGA melanoma; 19 m6A regulators displayed mutations, with the exception of only two genes (METTL14 and ALKBH5) in melanoma tissues." (PMID 34900983, 2021). "In mouse melanoma, depleting ALKBH5 improved the efficacy of anti–PD-1 therapy and had survival benefits." (PMID 34094986, 2021). "A recent study found that in anti-PD-1 therapy for melanoma, the deletion of ALKBH5 decreased the levels of infiltrating Tregs and polymorphonuclear myeloid derived suppressor cells (PMN-MDSCs), while the level of dendritic cells increased." (PMID 33777035, 2021). "Knockout of ALKBH5 in tumor cells enhanced the efficacy of immunotherapy, which supported the therapeutic value of ALKBH5 in melanoma immunotherapy." (PMID 34956201, 2021). "A small-molecule ALKBH5 inhibitor, which can enhance the effect of anti-PD-1 therapy for melanoma, was found in this study." (PMID 33777035, 2021). "ALKBH5 plays the role of eraser in m6A modification and has been proven to regulate suppressive immune cell accumulation in melanoma." (PMID 34079761, 2021). "As for the ‘erasers’, ALKBH5 promotes the progression of uveal melanoma and sensitizes tumors to cancer immunotherapy in melanoma." (PMID 34446007, 2021). "Further, molecular ALKBH5 inhibitors enhanced the efficacy of immunotherapy for melanoma, CRC, and other cancers." (PMID 34230220, 2021). "Intriguingly, both “writers” inhibition (METTL3 or METTL14) and “erasers” inhibition (FTO or ALKBH5) are proved to enhance the efficacy of anti-PD-1 blockade even in the same cancer (melanoma)." (PMID 34526985, 2021). "Eraser protein ALKBH5 modulates TIME, deletion of ALKBH5 in colon and melanoma syngeneic tumor model enhances the immune cells infiltration in TIME." (PMID 33718113, 2020). "For eraser genes, studies have found that knocking down FTO in mouse models could increase the tumor’s sensitivity to PD-1 therapy, while ALKBH5 promoted melanoma cell proliferation, migration, and invasion by acting on FOXM1 and ABCA1." (PMID 41301778, 2025). "To investigate the specific function of ALKBH5 in the progression of SKCM, we transfected cells with lentiviruses packaged with distinct shRNA sequence plasmids (shALKBH5#1, shALKBH5#2, and shALKBH5#3) and constructed stable ALKBH5-knockdown cells in melanoma A375 and A2058 cell lines." (PMID 38481816, 2024). "For example, targeting ALKBH5 in melanoma can enhance the effectiveness of PD-1 blockade." (PMID 39372415, 2024). "Interestingly, knocking down ALKBH5 affects the accumulation of multiple immune cells and transcriptional expression of tumor cells and similarly improves the sensitivity of melanoma to anti-PD-1 drug therapy." (PMID 39033180, 2024). "Through the UALCAN tool, we further discovered that the expression level of ALKBH5 was significantly higher in metastatic melanoma than in primary melanoma, indicating that ALKBH5 may play a dominant part in cancer progression and metastasis in SKCM." (PMID 38481816, 2024). "According to our results, high ALKBH5 expression was found in melanoma cell lines." (PMID 38252669, 2024). "In the future, we will explore the more well-round role and mechanism of MIR205HG in melanoma cell functions, collect clinical samples to validate our mechanism, and evaluate the role of ALKBH5 protein level in melanoma, so as to provide more theoretical references for melanoma treatment." (PMID 38252669, 2024). "Similarly, inhibiting ALKBH5 in melanoma enhances the efficacy of PD-1 blockade, patients with low expression of ALKBH5 are more likely to benefit from PD-1 blockade therapy." (PMID 39372415, 2024).
melanoma (continued). "Among these genes, we found that ATP-binding cassette transporter A1 (ABCA1), a functional membrane protein facilitating cholesterol efflux, presented the most consistent raised m6A level after ALKBH5 knockdown, and its mRNA level increased in shALKBH5 A375 melanoma cells compared to control cells." (PMID 38481816, 2024). "We further performed LC-MS analysis to show that the overexpression of ALKBH5 decreases overall m6A levels in melanoma cells, indicating that ALKBH5 might affect SKCM progression through m6A modification." (PMID 38481816, 2024). "The specific ALKBH5 inhibitor ALK-04 was found to improve anti-PD-1 therapy efficiency in melanoma." (PMID 36810281, 2023). "Recently, a study reported that ALKBH5 could promote a tumor-suppressive immune microenvironment by transporting lactate into extracellular space in melanoma." (PMID 36566230, 2022). "ALKBH5 deletion or inhibition enhances the efficacy of anti–PD-1 treatment in colorectal cancer and melanoma, suggesting ALKBH5 could represent a promising therapeutic target to enhance immunotherapy outcome in cancer patients." (PMID 35063010, 2022). "Knockdown of FTO increases m6A methylation of PD-1 in melanoma cells, while deletion of ALKBH5 (the ‘eraser’ of m6A) enriches the 3’UTR region of PD-L1 mRNA with m6A modifications, thereby promoting the degradation of PD-1 and PD-L1 in a YTHDF2-dependent manner." (PMID 35309316, 2022). "In melanoma, ALKBH5 knockdown effectively promotes sensitivity to anti-PD-1 treatment." (PMID 36071523, 2022). "Similarly, inhibition of ALKBH5 can make melanoma more sensitive to immunotherapy by regulating the expression of Mct4/Slc16a3, the lactose content and Treg cell number in tumour microenvironment." (PMID 36324258, 2022). "ALKBH5 deletion enhances the efficacy of anti–PD-1 therapy in melanoma patients." (PMID 35296338, 2022). "Then, the role of another m6A demethylase ALKBH5 is elucidated in melanoma immunology." (PMID 35693795, 2022). "Indeed, ALKBH5 mutation or expression are associated with response to anti–PD-1 immunotherapy in ICC and melanoma." (PMID 35063010, 2022). "Comparing primary melanoma and metastases, we found that ALKBH5, ELAVL1, FMR1, HNRNPA2B1, HNRNPC, IGF2BP1/2/3, KIAA1429, LRPPRC, RBM15, YTHDC1/2, YTHDF1/3, and ZC3H13 were significantly upregulated in metastases, while RBM15B and METTL3 were significantly upregulated in primary melanoma." (PMID 34993195, 2021). "ALKBH5 knockdown has been shown to sensitize melanoma and colon cancer to overcome the resistance for immunotherapy through downregulating prominent cells (Tregs and MDSCs), which immunosuppresses the anti-tumor immunity, while at the same time upregulating DCs." (PMID 34526985, 2021). "Based on their previous studies for the role of Mettl-3/14 in melanoma progression, the authors hypothesized that ALKBH5 might also have significant role in regulating the efficacy of anti-PD-1 therapeutics." (PMID 34571899, 2021). "Downregulation of ALKBH5 correlates with a positive response to PD-1 blockade in melanoma patients." (PMID 34422815, 2021). "Li and his colleague reported that ALKBH5 modulated Mct4/Slc16a3 expression and lactate content of the tumor microenvironment and promoted the composition of tumor-infiltrating Treg and myeloid-derived suppressor cells in melanoma and colorectal cancer, thus leading to resistance to immunotherapy." (PMID 35371987, 2022). "Additionally, ALKBH5 was found to regulate lactate production in melanoma and colon cancer." (PMID 35350378, 2022). "Importantly, a small-molecule ALKBH5 inhibitor enhanced the efficacy of cancer immunotherapy in melanoma, suggesting that the combination of FTO/ALKBH5 inhibition with anti-PD-1 blockade may reduce the resistance to immunotherapy in melanoma." (PMID 34526985, 2021).
melanoma (continued). "The tumor xenograft assay based on subcutaneous injection of sh-MIR205HG-treated melanoma cells showed that silencing MIR205HG suppressed tumor growth and reduced Ki67 positive rate by inactivating the JMJD2C/ALKBH5 axis." (PMID 38252669, 2024). "However, it is unclear whether MIR205HG regulates the JMJD2C/ALKBH5 axis to function in melanoma." (PMID 38252669, 2024). "This study aimed to investigate the role of long non-coding RNA MIR205 host gene (lncRNA MIR205HG) in proliferation, invasion, and migration of melanoma cells via jumonji domain containing 2C (JMJD2C) and ALKB homolog 5 (ALKBH5)." (PMID 38252669, 2024). "Generally, MIR205HG facilitated proliferation, invasion, and migration of melanoma cells through HuR-mediated stabilization of JMJD2C and increasing ALKBH5 transcription by erasing H3K9me3." (PMID 38252669, 2024). "Overall, our findings initially disclosed that MIR205HG downregulation retarded melanoma cell proliferation, invasion, migration, and in vivo tumor growth by repressing the JMJD2C/ALKBH5 axis." (PMID 38252669, 2024). "Thus, MIR205HG, JMJD2C, and ALKBH5 may be candidate therapeutic targets for melanoma treatment." (PMID 38252669, 2024). "In melanoma cells and CRC cells, ALKBH5 knockdown altered both the recruitment of the immune cell subpopulation and the transcriptome of tumor cells." (PMID 36810108, 2023). "In another study on “eraser” ALKBH5, researchers found that the knockout of ALKBH5 in mice with CT26 colorectal cancer or B16 melanoma significantly reduced tumor growth and prolonged the survival rate of mice during immunotherapy." (PMID 37427112, 2023). "ALKBH5 regulates the content of lactic acid and accumulation of tumor immune cells in the tumor microenvironment, so that ALKBH5 might serve as a potential therapeutic target to enhance the effect of immunotherapy in melanoma, colorectal, and potentially other cancer types." (PMID 35806168, 2022). "ALKBH5 promotes lactate generation and Tregs and MDSC accumulation by stabilizing Mct4/Slc16a3 mRNA in melanoma cells." (PMID 36071523, 2022). "For example, in melanoma, all of METTL3/14, ALKBH5 and FTO can modulate tumor response to anti-PD-1 therapy in mice." (PMID 35590394, 2022). "The findings showed that ZNF775, GBA, ALKBH5, ZFYVE1, and MIEF2 were significantly upregulated in Treg cells of metastatic melanoma compared with primary melanoma." (PMID 34159752, 2021). "More recently, a study also reported the efficacy of a specific ALKBH5 inhibitor, ALK04, in reducing tumor growth of melanoma cells." (PMID 33375621, 2020). "Targeting regulators like METTL3, METTL14, the IGF2BP family, ALKBH5, or FTO can enhance the efficacy of PD-1 blockade therapy in renal clear cell carcinoma, colorectal cancer, melanoma, NSCLC, breast cancer, hepatocellular carcinoma, and intrahepatic cholangiocarcinoma." (PMID 39372415, 2024). "The rescue experiments based on pcDNA3.1-ALKBH5 and si-MIR205HG-1 disclosed that ALKBH5 overexpression reversed the inhibitory role of silencing MIR205HG-1 in proliferation, invasion, and migration of melanoma cells." (PMID 38252669, 2024). "We found that knocking down ALKBH5 resulted in a decrease in SQSTM1 protein expression, which was negatively correlated with the degree of cell autophagy, promoting autophagy in A375 and A2058 melanoma cells." (PMID 38481816, 2024). "Hao and his colleagues found that EP300 could induce an increase in ALKBH5 expression to reduce the m6A level of FOXM1 mRNA by upregulating H3K27ac, resulting in enhanced FOXM1 mRNA levels and EMT cascade activation in melanoma." (PMID 36276071, 2022). "We did not determine the protein levels of ALKBH5 in melanoma cell lines." (PMID 38252669, 2024). "Besides, a specific inhibitor of ALKBH5, named ALK-04, could potentiate the efficacy of anti–PD-1 immunotherapy in melanoma treatment, providing a rational for future combination drug therapy." (PMID 35063010, 2022).
osteosarcoma (51 papers, 2020 to 2025). A usually aggressive malignant bone-forming mesenchymal neoplasm, predominantly affecting adolescents and young adults. "Our studie has demonstrated that the down-regulation of the demethylase ALKBH5 in osteosarcoma cells/tissues was associated with an increased m6A methylation compared with normal osteoblasts/tissues." (PMID 38233839, 2024). "Here, we aimed to explore the potential involvement of ALKBH5 in osteosarcoma and decipher the underlying cellular/molecular mechanisms." (PMID 33431791, 2021). "We have demonstrated the importance of ALKBH5-dependent m6A demethylation of RNAs for osteosarcoma tumor suppression with both gain- and loss-of-function approaches." (PMID 33431791, 2021). "Low ALKBH5 expression is linked to poorer survival in osteosarcoma patients." (PMID 39192357, 2024). "To determine whether ALKBH5 regulated m6A modification has a role in osteosarcoma cells, we conducted gain-of-function and loss-of-function studies." (PMID 33431791, 2021). "This research also discovered that ALKBH5-dependent m6A demethylation of RNAs significantly hinders the growth and mobility of osteosarcoma cells by directly and indirectly regulating Hippo-YAP signaling." (PMID 40180675, 2025). "In osteosarcoma cells, the enhanced expression of ALKBH5 weakens the stability of SOCS3 mRNA in an m6A-dependent manner, inactivating the STAT3 signaling pathway and increasing cell apoptosis." (PMID 40001461, 2025). "In osteosarcoma cells, the overexpression of ALKBH5 inhibits the m6A methylation of pre-miR-181b-1 and YAP-mRNA, which significantly triggers apoptosis, suggesting that ALKBH5 accelerates apoptosis." (PMID 40001461, 2025). "In osteosarcoma patients, RNA demethylase ALKBH5 is overexpressed and promotes osteosarcoma growth and metastasis." (PMID 39062505, 2024). "It is reported that, in osteosarcoma, ALKBH5‐mediated m6A demethylation of lncRNA PVT1 critically contributes to carcinogenesis via acting as an oncogene." (PMID 38098223, 2024). "Elevating ALKBH5 levels in osteosarcoma cells reduces m6A mRNA levels, inhibiting proliferation, inducing apoptosis, and causing cell cycle arrest." (PMID 39192357, 2024). "Overexpression of ALKBH5 significantly inhibited the growth, migration, invasion and apoptosis of osteosarcoma cells." (PMID 38233839, 2024). "As same in osteosarcoma, knockdown of ALKBH5 contributed to reducing the stability of LncRNA PVT1 in lung cancer cells." (PMID 37365581, 2023). "The downregulation of m6A demethylase ALKBH5 was correlated with increased m6A methylation in osteosarcoma cells/tissues compared to normal osteoblasts cells/tissues." (PMID 36835633, 2023). "ALKBH5 overexpression suppressed osteosarcoma cell growth and induced apoptotic cell death via the m6A-based direct/indirect regulation of YAP." (PMID 36835633, 2023). "Similar to the finding in NSCLC, ALKBH5 suppresses osteosarcoma progression via m6A-related direct/indirect YAP1 regulation." (PMID 35063010, 2022). "In osteosarcoma, ALKBH5-mediated m6a demethylation of lncRNA PVT1, an oncogene, was up-regulated, where it correlated with clinical stage, tumor size, and poor prognosis." (PMID 35734590, 2022). "The demethylase ALKBH5 was downregulated in osteosarcoma, and m6A methylation of pre-miR-181b-1 and YAP-mRNA was upregulated." (PMID 35090469, 2022). "ALKBH5 inhibits the progression of osteosarcoma through m6A-dependent epigenetic silencing of the premiR-181b-1/YAP signaling axis." (PMID 35945641, 2022). "According to Yuan’s study, ALKBH5 overexpression markedly reduces the proliferative, migratory and invasive features of osteosarcoma cells, while triggering apoptosis." (PMID 35063010, 2022). "METTL3 and ALKBH5 expression levels are upregulated in doxorubicin-resistant osteosarcoma cells, while METTL14 expression is downregulated." (PMID 34094986, 2021). "Recently, Chen et al25 revealed that ALKBH5‐mediated m6A modification of lncRNA PVT1 is involved in the occurrence of osteosarcoma." (PMID 32960485, 2021).
osteosarcoma (continued). "In line with the results for U2OS, these effects of ALKBH5 were further confirmed in another osteosarcoma cell line Saos2." (PMID 33431791, 2021). "We further applied immunohistochemistry (IHC) assays to measure ALKBH5 protein expression in osteosarcoma tissue microarrays (TMAs) containing 102 tissue cores." (PMID 33431791, 2021). "First, m6A demethylase ALKBH5 expression levels are decreased, and m6A methylation substantially increased in human osteosarcoma." (PMID 33431791, 2021). "ALKBH5 overexpression reduced osteosarcoma tumor growth as evidenced by lower tumor volumes and weights, and this effect was abrogated by co-transfection of overexpressed YAP." (PMID 33431791, 2021). "ALKBH5 overexpression significantly suppressed osteosarcoma cell growth, migration, invasion, and trigged cell apoptosis." (PMID 33431791, 2021). "Second, ALKBH5 exerts tumor-suppressive effects as its overexpression inhibits osteosarcoma cell growth, migration, invasion, and its silence produces the opposite effects." (PMID 33431791, 2021). "Our data showed increases in both mRNA and protein expression of YAP after ALKBH5 overexpression in osteosarcoma cells." (PMID 33431791, 2021). "In osteosarcoma cells, ALKBH5-mediated mA modification of PVT1 contributes to osteosarcoma tumorigenesis." (PMID 33955330, 2021). "We discovered downregulated levels of demethylase ALKBH5 were correlated with increased m6A methylation in osteosarcoma cells/tissues compared with normal osteoblasts cells/tissues." (PMID 33431791, 2021). "Our m6A-RIP-microarray data demonstrated that pre-miR-181b-1 was enriched in m6A-RIP fraction with ALKBH5 inhibition, which suppressed osteosarcoma tumor growth." (PMID 33431791, 2021). "Despite ALKBH5 has been identified to contribute significantly to physiological osteogenesis, ALKBH5 mediates osteosarcoma (OS) tumorigenesis via demethylation of plasmacytoma variant translocation one, a tumorigenic lncRNA." (PMID 33511112, 2020). "Furthermore, ALKBH5-mediated m6A deficiency increases the expression of USP22 and RNF40 in osteosarcomas, promoting osteosarcoma cell growth and proliferation." (PMID 40001461, 2025). "In addition, ALKBH5-induced m6A demethylation suppresses growth, migration, and invasion of osteosarcoma cells by enhancing the RNA stability of NOTCH1 and NOTCH2." (PMID 40180675, 2025). "Similarly, the m6A demethylation of lncRNA PVT1 by ALKBH5 promotes the development of osteosarcoma, highlighting the importance of chromatin modifiers in regulating m6A gene expression." (PMID 40225569, 2025). "Therefore, ALKBH5-based m6A demethylation opens up a new strategy for replacement therapy against osteosarcoma through m6A-correlated posttranscriptional regulation of pre-miRNA-181b-1 and Yes-associated protein 1 (YAP)." (PMID 35090469, 2022). "In addition, upregulation of ALKBH5 expression also contributes to chemoresistance in osteosarcoma patients and predicts worsening of their metastasis-free survival." (PMID 35846376, 2022). "Furthermore, lower protein expression of ALKBH5 was detected in human osteosarcoma tissues as compared with normal bone tissues." (PMID 33431791, 2021). "Under such a theme, we proposed that ALKBH5 is a tumor-suppressor gene, and ALKBH5 overexpression might be a new approach of replacement therapy for the treatment of human osteosarcoma." (PMID 33431791, 2021). "In addition, upregulation of ALKBH5 expression also contributes to chemoresistance and predicts worse metastasis-free survival in patients with osteosarcoma." (PMID 34094986, 2021). "Moreover, elevated ALKBH5 decreased, or depleting ALKBH5 increased the colony-formation capacities of U2OS osteosarcoma cells." (PMID 33431791, 2021). "Therefore, ALKBH5-based m6A demethylation suppressed osteosarcoma cancer progression through m6A-based direct/indirect regulation of YAP." (PMID 33431791, 2021).